ZNF66 (zinc finger protein 66)
Description:
May be involved in transcriptional regulation.
Synonyms: ZNF66P; FLJ16537
Tractability: PROTAC: ubiquitination databases record sites on it.
Gene: Protein-coding gene on chromosome 19 (20,776,304 to 20,810,361, forward strand). Ensembl gene ENSG00000160229.
Subcellular location: Nucleus
Gene Ontology:
Molecular function: DNA-binding transcription factor activity, RNA polymerase II-specific; RNA polymerase II cis-regulatory region sequence-specific DNA binding
Biological process: regulation of DNA-templated transcription; regulation of transcription by RNA polymerase II
Cellular component: nucleus
Genetic constraint (gnomAD): Loss-of-function variants: 6 observed, 10.62 expected, observed/expected ratio (o/e) 0.56, 90% interval 0.31 to 1.12. The upper end of that interval is the gene's LOEUF score, 1.12, which puts it in group 4 of 6, group 1 being the genes least tolerant of losing a copy. Missense variants: 184 observed, 185.53 expected, observed/expected ratio (o/e) 0.99, 90% interval 0.88 to 1.12. Synonymous variants: 77 observed, 60.2 expected, observed/expected ratio (o/e) 1.28, 90% interval 1.06 to 1.55.
Homologues: Paralogues in human: ZNF737 (75% identical), ZNF626 (68% identical), ZNF92 (68% identical), ZNF257 (64% identical), ZNF675 (64% identical), ZNF723 (64% identical), ZNF98 (64% identical), ZNF253 (64% identical), ZNF431 (63% identical), ZNF273 (63% identical), ZNF430 (63% identical), ZNF730 (62% identical), and 6 more.
Diseases named in the same sentence as ZNF66 in open-access papers:
ZNF66 is named in the same sentence as 4 diseases in open-access papers, as found by Europe PMC text mining. Sharing a sentence is not in itself a finding about the gene and the disease. The quoted sentences say what the papers report.
breast carcinoma (1 paper, 2025). "Cathepsin E can mediate the effects of APBB1IP, NT5C3B, and ZNF66 on HER2-negative breast cancer, as well as the effects of DHRS9, CDK12, and CD247 on HER2-positive breast cancer." (PMID 39944834, 2025).
cancer (1 paper, 2020). A tumor composed of atypical neoplastic, often pleomorphic cells that invade other tissues. "The 8-mRNAsi based prognostic model in our signatures includes RGS16, LYVE1, hnRNPC, ANP32A, AIMP1, ZNF66, PIK3R3, and MAP2K7, in which several genes have been reported to be linked with stemness features or be involved in cancer progression." (PMID 33329703, 2020).
ZNF66 also shares sentences with these, for which no sentence is quoted: head and neck cancer (1 paper); migraine (1).